RN7SL271P (RNA, 7SL, cytoplasmic 271, pseudogene)
Gene: Miscellaneous RNA gene on chromosome 3 (71,827,177 to 71,827,471, forward strand). Ensembl gene ENSG00000239250.
Homologues: Orthologues: chimpanzee Metazoa_SRP (99% identical), macaque Metazoa_SRP (88% identical). Paralogues in human: RN7SL1 (81% identical), RN7SL2 (81% identical), RN7SL3 (80% identical), RN7SL296P (80% identical), RN7SL357P (79% identical), RN7SL278P (79% identical), RN7SL714P (79% identical), RN7SL126P (78% identical), RN7SL566P (78% identical), RN7SL786P (78% identical), RN7SL88P (78% identical), RN7SL147P (77% identical), and 704 more.